PPARG (peroxisome proliferator activated receptor gamma)
Diseases named in the same sentence as PPARG in open-access papers (continued):
Sharing a sentence is not in itself a finding about the gene and the disease.
Obesity (continued). "In vitro and in vivo studies of Tecomella undulata ethyl acetate extract revealed anti-obesity efficacy by downregulating adipogenesis and lipogenesis via sirtuin 1 (SIRT1), adiponectin, and peroxisome proliferator activated receptor γ (PPARγ)." (PMID 36834657, 2023). "AMPK activation inhibits downstream targets involved in obesity, such as ACC1 and FAS, which are involved in lipogenesis, and PPARγ, C/EBPα, and SREBP-1C, which are involved in adipocyte differentiation and lipid accumulation." (PMID 36839173, 2023). "Here, we found that inhibition of PPARγ by BZ26 inhibited the differentiation of mature adipocytes to CAAs, thereby inhibiting obesity-related inflammation and breast cancer growth and metastasis." (PMID 37649895, 2023). "During the screening of small molecules that regulate obesity-related metabolic syndrome, BZ26, a novel GW9662 derivate that was identified as a potential ligand of PPARγ via molecular docking studies." (PMID 37649895, 2023). "Concurrently, the decomposition of short-chain fatty acids by Lb. induces PPARγ to increase the expression of mitochondrial uncoupling protein 2 and increase the ratio of AMP to ATP, reduce obesity induced by an HFD, and reduce host TG involvement." (PMID 36771383, 2023). "The treatment with PIO was capable of improving this IR and reduced PH, by reversing the decreased expression of adiponectin and PPARg, highlighting the mechanisms involved in PAH patients with IR in obesity, and the potential use of PIO as a treatment." (PMID 38239990, 2023). "Although Nrf2 is generally required for HFD-induced obesity, as mentioned, constitutive Nrf2 activation by Keap1 KD also inhibited HFD-induced obesity by decreasing PPARγ and C/EBPα." (PMID 37892226, 2023). "PPARγ has relevance to both T2DM and AD, as PPARγ can regulate obesity, diabetes and neuroinflammation." (PMID 35128745, 2022). "PPARG is mainly responsible for lipid catabolism, and it is related to NAFLD, obesity, diabetes, arteriosclerosis, etc.." (PMID 36199550, 2022). "SOH reduced adipogenesis by inhibiting the expression of pro-adipogenic C/EBPα, C/EBPβ, and PPARγ in 3T3-L1 cells, leading to decreased dietary intake and body weight in mice with HFD-induced obesity." (PMID 35631305, 2022). "Owing to its relevance in adipogenesis, it appears that the inhibition of PPARγ, C/EBPα, or SREBP plays a pivotal role in obesity treatment." (PMID 36092543, 2022). "They reported that adipogenic and insulin signaling genes (CEBPB, PPARG, ADIPOQ, IRS-1, IRS-2, GLUT4, among others) were downregulated in obesity." (PMID 36432612, 2022). "Future studies are needed to confirm the upstream regulator of the BFE-mediated PPARγ pathway, as well as the expression of lipolysis-related genes, which would support the development of BFE for anti-obesity therapy." (PMID 36364945, 2022). "Our studies also showed that inhibition of Rab2A expression alleviated hepatic lipid deposition in western diet-induced obesity (DIO) mice by reducing the protein level of PPARγ and the expression of PPARγ target genes." (PMID 35061665, 2022). "In this study, our cohort of women made it possible to relate SFRP5, WNT5A and PPARγ mRNA abundance in SAT and VAT with obesity and NAFLD." (PMID 36077270, 2022). "Currently, drugs from natural sources that specifically inhibit peroxisome proliferator-activated receptor gamma (PPARγ) and CCAAT enhancer-binding protein alpha (C/EBPα) expression are being targeted for the treatment of obesity." (PMID 35208957, 2022). "New interventions targeting LEP, NOTCH1, SPRY1, PPARG, ID2, and CIDEA gene network, in addition to what already is going on, can be designed for treatment and prevention of both obesity and tumors." (PMID 35395810, 2022). "At the same time, PPARγ is related to the regulation of obesity factors, such as ADPN and LEP; changes in obesity factors are the best predictors of insulin sensitivity." (PMID 35407014, 2022).
Obesity (continued). "In a previous study using an in vitro obesity model, ononin showed anti-adipogenic capacity by upregulating SIRT1 and inhibiting PI3K, PPARγ, and adiponectin." (PMID 35990844, 2022). "Although the precise molecular mechanisms underlying obesity remain unclear, recent studies indicated that CCAAT/enhancer-binding protein alpha (C/EBPα), C/EBPβ, and peroxisome proliferator-activated receptor gamma (PPARγ) are important regulators released during adipogenesis." (PMID 35631305, 2022). "Collectively, compounds that inhibit PTPN6 and antagonize PPARγ are believed to exhibit potential effects on T2DM and obesity." (PMID 35563411, 2022). "Thus, the anti-obesity effect of UDE may be due in part to the downregulation of PPARγ." (PMID 34099594, 2021). "Our study discovers a novel key function for the TBX15 TF in trans regulating an adipose co-expression network of 347 adipose, mitochondrial, and metabolically important genes, including PPARG, KLF15, PPARA, ADIPOQ, and 35 obesity GWAS genes." (PMID 34340684, 2021). "We demonstrate that upon p62 inactivation, NBR1 represses the activity of PPARγ, establishing an unexplored p62/NBR1-mediated paradigm in adipocyte thermogenesis that is critical for the control of obesity." (PMID 34001883, 2021). "In their study, they showed that SIRT1 promotes a beneficial metabolic effect through interaction with PPARγ, leading to insulin sensitization, and implied a therapeutic potential of TZD and SIRT1 agonist combination therapy for obesity." (PMID 33467433, 2021). "This phenotype was accompanied by increased hepatic PPARγ and adiponectin expression, along with overall improvement in systemic insulin sensitivity and HFD-induced obesity." (PMID 34943809, 2021). "On the other hand, the mRNA levels of CD206, IL-10, Fizz1, Mrc1 and PPARγ were reduced in obesity group, and PDX treatment significantly increased the levels of CD206, Fizz1 and PPARγ in epididymal adipose tissue." (PMID 35185543, 2021). "Synthetic PPARγ antagonists, GW9662 and bisphenol A diglycidyl ether, have also been reported to improve insulin resistance and obesity." (PMID 33494317, 2021). "We observed a positive correlation between PPARγ and PDK1/2 expression in visceral adipose tissue obtained from individuals with various degrees of obesity." (PMID 34552205, 2021). "For example, overexpression of PPARγ through increasing physical activity performance, UCP2 expression, and thereby mitochondrial metabolism decreases fat mass and obesity." (PMID 34458651, 2021). "Our study discovers a new key function for the TBX15 TF in trans regulating an adipose co-expression network of 347 adipose, mitochondrial, and metabolically important genes, including PPARG, KLF15, PPARA, ADIPOQ, and 35 obesity GWAS genes." (PMID 34340684, 2021). "Accordingly, it has been shown in rodent models that maternal obesity modulates the expression of pro-adipogenic genes such as C/EBPβ, ZFP423, and PPARγ in the offspring, thus reprogramming adipogenesis." (PMID 34371900, 2021). "It has been reported that downregulation of PPARγ and C/EBPα expressions ameliorated HFD-induced obesity through inhibiting adipogenesis." (PMID 34174964, 2021). "As for IGFBP-3, this protein inhibits adipocyte differentiation and impacts the peroxisome proliferator-activated receptor-gamma (PPARγ) system, suggesting a role for IGFBP-3 in the pathogenesis of obesity and IR." (PMID 32911852, 2020). "Additionally, anti-obesity mechanisms related with concrete seaweed components, such as phlorotannins, that target the inhibition of adipocyte differentiation or fucosterol, that decreases the expression of the adipocyte marker proteins PPARγ and CCAAT/enhancer-binding protein alpha were reported." (PMID 32102343, 2020). "Resveratrol has been proposed as an anti-obesity agent that increases fatty acid oxidation through upregulation of AMPK and PGC-1α and downregulation of peroxisome proliferator-activated receptor gamma and CCAAT-enhancer-binding protein." (PMID 32752111, 2020).
Obesity (continued). "The significant genes in GWAS results (CALCR, PLAG1, INSIG2, PPARG, BMP5, S100A10) also have been identified to have relationship with growth performance and obesity of adipose tissue for pig and cattle." (PMID 33264312, 2020). "LBP can suppress the PA-induced osteoblast apoptosis through the miR-200b-3p/Chrdl1/PPARγ axis, which has also verified that LBP shows certain protection on the obesity-induced osteoporosis." (PMID 33447177, 2020). "Compared to controls, reduced expression levels of APCDD1 and adipogenic markers (PPARG and C/EBPA) were also observed in scAT of patients with obesity." (PMID 33207733, 2020). "This adipogenesis dysregulation can be attributed to the pro-inflammatory environment of WAT in obesity, where pro-inflammatory cytokines (e.g., TNFA) can exert anti-adipogenic effects on adipocytes through downregulation of PPARG, C/EBPA and FABP4 expression." (PMID 33207733, 2020). "It has been reported that the raise of SIRT-1-mediated PPARγ deacetylation further facilitated the interaction of PPARγ and PRDM16, which eventually promoted brown features in white adipocytes to prevent obesity." (PMID 33551999, 2020). "Several classes of anti-obesity and anti-diabetes medications (such as metformin, 5-Aminoimidazole-4-carboxamide ribonucleotide (AICAR), and PPARγ agonists) are known to modulate the immune system and result in improved insulin sensitivity." (PMID 33335527, 2020). "We assumed that a better understanding of the JNK signaling pathway and its relationship with PPARγ, NF-κB, PTP1B signaling pathways are necessary for a new drug targeting the treatment of obesity and mood disorders." (PMID 32942585, 2020). "To investigate the possible mechanism of AMPK-mediated protective effects of crocin against obesity and type 2 diabetes, we evaluated the changes of CDK5/PPARγ signaling." (PMID 32596392, 2020). "Gpx1-deficient epididymal adipocytes were also found to have lower diameter despite normal differentiation status (PPARγ, AP2, and C/EBP), being in agreement with the overall resistance of Gpx1−/− mice to diet-induced obesity." (PMID 32344656, 2020). "Natural products can enhance anti-obesity effects by downregulating the expression of adipogenic transcriptional factors such as SREBP-1c, C/EBPα, and PPARγ in 3T3-L1 preadipocytes." (PMID 31838799, 2020). "Fibrates and thiazolidinediones (TZDs) activate intracellular nuclear receptors such as PPARγ and TZDs, and reduce the expression of leptin and TNF-α, thereby reducing the inflammatory process by obesity." (PMID 30818882, 2019). "Here we dissected the specific role of high-fat-diet (HFD)-induced obesity and vascular smooth muscle cell (VSMC)-PPARγ for remodelling of small pulmonary arteries." (PMID 30813929, 2019). "Taken together, our findings show that LKU4 administration facilitates browning of iWAT by promoting PPARγ-PGC-1α interaction by increasing lactate levels, at least in part, which ameliorates diet-induced obesity in mice." (PMID 31882939, 2019). "Together, these data reveal that LKU4 facilitates browning of white adipocytes through the PPARγ-PGC-1α transcriptional complex, at least in part by increasing lactate levels, leading to inhibition of diet-induced obesity." (PMID 31882939, 2019). "While most evidence shows that PPARγ expression increases in diabetic or obesity models of NAFLD and suggest a deleterious and lipogenic role for hepatic PPARγ in NAFLD, others suggest a beneficial role for PPARγ." (PMID 30832407, 2019). "An involvement of FABP4 in the pathogenesis of obesity and insulin resistance seems to be mediated via FABP4-dependent peroxisome proliferator-activated receptor γ (PPARγ) inhibition." (PMID 30857223, 2019). "Lipid accumulation plays an important role in the development of obesity and is regulated by various adipogenic-specific proteins including SREBP-1c, PPARγ, and C/EBPα, as well as lipogenic enzymes such as FABP4 and FAS." (PMID 31717668, 2019).
Obesity (continued). "Concomitantly, a recent study using liver-specific SHP1 KO mice showed that these mice were protected from obesity-induced severe NAFLD, which was possibly a result of reduced PPARγ promoting insulin resistance and hepatic inflammation." (PMID 31236111, 2019). "Therefore, targeting PPARγ may represent a promising approach for the management of obesity." (PMID 30742088, 2019). "In a recent study, we reported that DBZ (danshensu bingpian zhi), a putative PPARγ agonist, simultaneously prevented HFD-induced obesity-related metabolic syndrome and gut dysbiosis." (PMID 30060458, 2018). "The free fatty acid derivatives released during lipolysis can serve as intrinsic ligands for PPARγ and can impair insulin-signaling; hence, the regulation of ATGL and HSL are important in relation to obesity, T2D, and related metabolic disorders." (PMID 30248999, 2018). "HDAC3 inhibits PPARγ and nuclear transcription factor-κB (NF-κB), and HDAC3 inhibition restores PPARγ function in obesity." (PMID 29258184, 2017). "In addition, PPARγ was increased significantly by 2.84-fold (p = 0.0041), suggesting the hypoglycemic mechanism of CB0313.1 may be associated with an attenuation of energy metabolic dysfunction and obesity." (PMID 28765642, 2017). "Overall, our data suggest that CACUL1 tightly regulates PPARγ signaling through the mutual opposition between SIRT1 and LSD1, providing insight into its potential use for anti-obesity treatment." (PMID 29233982, 2017). "Consistent with previous reports, we also observed that elevated PPARγ transcriptional activity in RORαLKO mice are downregulated after treatment of GW9662, resulting in decrease of diet-induced hepatic steatosis and obesity." (PMID 28757615, 2017). "Therefore, obesity may directly contribute to the pathogenesis of a certain nutritional disease, and partially attributing the contribution of obesity to nutritional disease to PPARG is reasonable." (PMID 29258237, 2017). "In this study, our findings unfold the molecular regulation of obesity by which AWL effectively inhibited the expression of C/EBPβ, C/EBPα, and PPARγ at the mRNA and protein levels." (PMID 28555033, 2017). "Using this approach we have identified the nuclear hormone receptor PPARG, the metalloproteinase ADAMTS5, and the aldo-keto reductase AKR1B10 as potential drug targets for treatment of osteoporosis and obesity." (PMID 27562730, 2016). "Male Swiss mice with obesity and hyperglycemia induced by high fat diet were treated with vehicle, rosiglitazone (4 mg/kg/d) or the TZD-derived partial PPARγ agonist GQ-16 (40 mg/kg/d) for 14 days." (PMID 27138164, 2016). "Consequently, defective GATA2 and GATA3 expression is associated with obesity, while expression of GATA2 and GATA3 inhibits adipogenesis and traps cells at the preadipocyte stage, which could be as a result of direct suppression of PPARγ." (PMID 26797605, 2016). "In the livers of mice with dietary obesity (HFD) or genetic obesity (ob/ob), PPARγ protein levels are dramatically increased, but this increment did not elevate the expression of ATGL." (PMID 27759039, 2016). "The anti-obesity effect of TPEE is likely due to reduced expression of lipogenic genes such as FAS, SREBP-1c, PPARγ and leptin and up regulation of adiponectin and AMPK-1α." (PMID 25887331, 2015). "The variants of genes like PPARG, ADIPOQ, and ENPP1 which act at the level of insulin resistance have been shown to increase the risk of T2DM only in obese populations and hence it has been suggested that T2DM risk contribution of gene polymorphism may be modulated by obesity status." (PMID 26491214, 2015). "A regulatory cascade involving PPARγ and TWIST1 was found in low-grade chronic inflammation in humans, which is a major characteristic of obesity and results from deregulated white adipose tissue function." (PMID 25128964, 2014). "The expression level of PPARγ and phospho-Akt was significantly lower in the CCC-treated HFD rats than that in the HFD obesity rats." (PMID 25181477, 2014).
Obesity (continued). "In obesity cytokine and high fat diet induced CDK5 mediated phosphorylation of PPARγ is reported to dysregulate expression of a number of genes including adiponectin." (PMID 25143786, 2014). "As the master regulator of fat cell formation, peroxisome proliferator-activated receptor gamma (PPARG) is required for the accumulation of adipose tissue and hence contributes to obesity." (PMID 24466299, 2014). "Reduced expressions of fatty acid synthetase, PPARγ, and LPL in adipose tissue suppress the onset of obesity." (PMID 23365609, 2013). "This includes for example the regulation of SIRT1, a protein known to activate PPARG and SREBF1, which contributes to hepatic steatosis in obesity upon ubiquitination and proteasomal stimulation of its degradation." (PMID 24324835, 2013). "Our study shows that RF is capable of inhibiting the differentiation of 3T3-L1 adipocytes through the modulation of PPARγ, C/EBPα, and AMPK, suggesting that it has a potential for therapeutic application in the treatment or prevention of obesity." (PMID 24288561, 2013). "Genetic variations in the obesity-related genes beta-2 adrenergic receptor (ADRB2), beta-3 adrenergic receptor (ADRB3), insulin induced gene 2 (INSIG2), and peroxisome proliferator-activated receptor gamma (PPARγ) are also included in our study." (PMID 22355322, 2012). "Reduced expressions of fatty acid synthetase, PPARγ and LPL in the liver suppress the onset of obesity and fatty liver." (PMID 21799697, 2011). "Whilst D9D/SCD1 is positively correlated with PPARγ to increase lipogenesis in adipocytes, the significance of reducing the D9D/SCD1 expression to reverse obesity has been constantly discussed." (PMID 20525346, 2010). "T2D, age, obesity- all increases ROS that in turn increases lipid oxidation, via ROS/FOXO/PPARG/PPARA/β-catenin regulation leads to PPARG activation and repression of Wnt-signaling." (PMID 20942928, 2010). "Furthermore, activation of PPARγ in adipose tissue may also have positive effects on pancreatic β-cell function and help to minimize the aggravated paracrine relationship between adipocytes and macrophages seen in obesity." (PMID 20182551, 2009). "In contrast, overweight, obesity, increased lipogenesis, and hepatic steatosis exacerbate SHBG synthesis inhibitory factors (e.g., chicken ovalbumin upstream promoter transcription factor (COUP-TF) or peroxisome proliferator-activated receptor gamma (PPARγ))." (PMID 40427034, 2025). "Ant Fr also inhibited lipid accumulation by reducing the expression of PPARγ, CCAAT, C/EBPα, aP2, FAS, and LPL and enhancing the activation of the AMPK signaling pathway, demonstrating a positive impact on treating or controlling obesity." (PMID 39968092, 2025). "Obesity-induced inflammation is thought to be the mechanism leading to IR and NAFLD, and HFD inhibits phosphorylation of AMPK-TBC1D1 signaling, increases protein levels of PPARγ, and ultimately promotes hepatic fat accumulation." (PMID 41150739, 2025). "The alteration of certain obesity-promoting genes (e.g., FTO and peroxisome proliferator-activated receptor gamma gene (PPARγ)) and anti-obesity genes (e.g., LEP, GLP-1R, and POMC) may be associated with obesity." (PMID 40868241, 2025). "Importantly, PMFs have demonstrated specific anti-obesity mechanisms through AMP-activated protein kinase activation, fatty acid oxidation promotion, and peroxisome proliferator-activated receptor-gamma (PPARγ) modulation." (PMID 41228394, 2025). "The study revealed a close correlation between obesity and the AKT1 and PPARG genes." (PMID 39409084, 2024). "Through the activation of PPARγ by PGC-1α, there is a coordinated regulation of lipid metabolism, energy homeostasis, and thermogenesis, making this interaction a pivotal point in the management of metabolic diseases such as obesity and diabetes." (PMID 39195446, 2024).